HGF (hepatocyte growth factor)
Diseases named in the same sentence as HGF in open-access papers (continued):
Sharing a sentence is not in itself a finding about the gene and the disease.
migraine (4 papers, 2017 to 2025). "A mendelian randomization study concluded HGF to be a potential causative factor for migraine onset." (PMID 39044165, 2024). "Among them, HGF displayed a positive association with migraine risk (OR, 1.004; 95% CI: [1.001–1.008]; P = 0.022)." (PMID 37938611, 2023). "The results showed that hepatocyte growth factor (HGF) was positively associated with the risk of migraine (odds ratio [OR], 1.004; 95% confidence interval [CI], 1.001–1.008; P = 0.022)." (PMID 37938611, 2023). "This suggests that HGF may cause migraine by affecting the release of neurotransmitters." (PMID 37938611, 2023). "Our results suggest that HGF may be a potential cause of migraine." (PMID 37938611, 2023). "In conclusion, although research on HGF in migraine is still in its early stages, our study provides a promising research direction for future studies, which will help to better understand the role of HGF in the pathogenesis of migraine." (PMID 37938611, 2023). "Although there is limited research on HGF and IL-2 in migraine, our study suggests that they play a significant role in migraine pathogenesis." (PMID 37938611, 2023). "Therefore, it can be concluded that HGF may play a dominant role in the early onset of migraine, while IL-2 is more likely to be downstream in the disease progression." (PMID 37938611, 2023). "Cytokines CXCL1, HGF, and LIF appear to be also higher in at least one patient with migraine with aura." (PMID 28900389, 2017).
monoclonal gammopathy of undetermined significance (4 papers, 2014 to 2025). "Abraham et al24 showed that circulating concentrations of HGF were substantially higher in patients with AL than in patients with monoclonal gammopathy of undetermined significance." (PMID 40570404, 2025). "Among these, it has been observed that hepatocyte growth factor (HGF) has a critical role in disease progression from monoclonal gammopathy of undetermined significance (MGUS) to MM." (PMID 35582373, 2021).
neuropathy (4 papers, 2018 to 2022). A disorder affecting the nervous system that manifests with pain, tingling, numbness, and/or muscle weakness. "In an effort to develop an effective treatment method for painful neuropathy, we have been exploring the possibility of using plasmid expression human hepatocyte growth factor (HGF)." (PMID 29913557, 2018).
nonalcoholic steatohepatitis (4 papers, 2016 to 2024). "On the other hand, patients with the most severe form of NAFLD, i.e., nonalcoholic steatohepatitis (NASH) present a significant increase in circulating levels of HGF." (PMID 31547124, 2019).
pancreatitis (4 papers, 2014 to 2024). Inflammation of the pancreas. "In the interesting group of patients who progressed to severe pancreatitis (that is, developed persistent organ dysfunction) during their hospital stay, IL-8, HGF, and granulocyte colony-stimulating factor were significantly higher than in those who did not." (PMID 25673030, 2014).
rheumatic disease (4 papers, 2021 to 2025). "Hepatocyte growth factor was significantly increased in the group of rheumatic diseases patients (SSc+ORD) compared with HC, while chemokine (C-C motif) ligand 5 (CCL5) was significantly higher in SSc patients compared with ORD and HC." (PMID 33313931, 2021). "HGF levels inversely correlated with the gestational week at delivery and when the disease groups were analysed separately, a significant inverse correlation was seen in the rheumatic disease patients group (SSc+ORD), but not in HC." (PMID 33313931, 2021).
schizophrenia (4 papers, 2020 to 2024). A major psychotic disorder characterized by abnormalities in the perception or expression of reality. "Recently, HGF was found to be upregulated in a study in which the authors used fibroblasts collected from a unique population of schizophrenia patients in northern Sweden." (PMID 34179015, 2021). "PANSS total score was significantly and positively correlated with CSF HGF and S100B levels in patients with schizophrenia {r = 0.34, p = 0.001 (significant even after correction) and r = 0.28, p = 0.007}." (PMID 32439851, 2020). "A genetic implication of HGF and MET in the development of brain emerges from the literature, and various alterations in the HGF-MET pathway correlate with features of some NDDs such as ASD, schizophrenia, and non-syndromic hearing loss." (PMID 34179015, 2021). "The upregulation of HGF in schizophrenia was reported in the CommonMind Consortium (CMC) study." (PMID 34179015, 2021). "Few studies also revealed a genetic implication of HGF gene in schizophrenia." (PMID 34179015, 2021). "The genes HGF, PRRT2, EGR1, EGR3, C11orf87, TLR3 and PLEKHH2 have been reported in either genetic analysis or gene expression analysis of schizophrenia, and were all upregulated in fibroblasts from patients in our study." (PMID 31959813, 2020). "CSF HGF level showed a positive correlation with PANSS total, positive, and general scores in patients with schizophrenia and HAMD-21, core, sleep, activity, somatic anxiety, and delusion subscale scores in patients with MDD, respectively." (PMID 32439851, 2020).
scleroderma (4 papers, 2006 to 2016). Scleroderma is a rare autoimmune connective tissue disorder characterized by abnormal hardening of the skin and, sometimes, other organs. "Previously, we demonstrated that the antifibrotic activity of HGF is different in LF isolated from African American and Caucasian scleroderma patients." (PMID 27584154, 2016). "HGF treatment of scleroderma lung fibroblasts as well as HGF treatment of TGFβ-treated normal lung fibroblasts transfected with wild type MET is associated with decreased collagen, connective tissue growth factor (CTGF, CCN2) and smooth muscle α-actin (SMA)." (PMID 27584154, 2016). "In a previous study, we demonstrated that HGF gene transfection improved dermal sclerosis in mouse model of scleroderma." (PMID 25332857, 2014). "Addition of HGF to fibroblast cultures of scleroderma patients significantly decreased collagen production and increased MMP-1 expression and activity." (PMID 25332857, 2014). "To clarify whether modulation of IL-4 and TGF-β has a role in the prevention of sclerosis induced by HGF gene transfection in the scleroderma model mouse, we examined the mRNA expression of these cytokines." (PMID 17049072, 2006). "We previously demonstrated that HGF-induced down regulation of collagen and CCN2 in scleroderma LF is mediated by a MAPK-dependent pathway." (PMID 27584154, 2016). "Recently, HGF has been shown to downregulate TGF-β1 expression and prevent dermal sclerosis in a murine bleomycin-induced scleroderma model." (PMID 17049072, 2006).
T cell lymphoma (4 papers, 2019 to 2024). "The expression of c-MET and its ligand HGF in NK/T-cell lymphoma cell lines, nasal NK/T-cell lymphoma specimens, and patient serum samples was confirmed." (PMID 39664377, 2024). "Natural killer/T cell lymphoma (NKTCL) cells were found to produce HGF and activate the HGF/c‐Met signalling pathway for tumour cell proliferation in an autocrine manner." (PMID 34651428, 2021). "HGF was shown to promote NK/T cell lymphoma proliferation in an autocrine manner." (PMID 39664377, 2024). "c-MET and HGF are expressed in natural killer/ T cell lymphoma cell lines and in nasal NK/T cell lymphoma specimens thus suggesting that also NK/T cell lymphoma proliferation may be induced through an autocrine loop." (PMID 30642077, 2019). "These IGF2 and HGF-induced tumors showed the same anatomic distribution and histology of CD3(+)/CD20(-) T cell lymphoma." (PMID 34539876, 2021).
acute lung injury (3 papers, 2011 to 2019). A condition of lung damage that is characterized by bilateral pulmonary infiltrates (pulmonary edema) rich in neutrophils, and in the absence of clinical heart failure. "Mesenchymal stem cells (MSCs) have been shown to alleviate acute lung injury (ALI) via paracrine hepatocyte growth factor (HGF) and to induce the differentiation of dendritic cells (DCs) into tolerogenic dendritic cells (DCregs) and participate in the immune response." (PMID 31801626, 2019). "On the other hand, HGF levels in pulmonary edema fluids from non-survivors were noted to be higher than those in survivors of acute lung injuries." (PMID 21429184, 2011).
adenoma (3 papers, 1997 to 2019). A neoplasm arising from the epithelium. "Moreover, the hepatocyte growth factor (HGF)-mediated growth of intestinal organoids or adenomas in vitro depends on CD44v4-10 rather than CD44s8." (PMID 30631039, 2019). "Functional expression of these oncoproteins induced the adenoma-to-carcinoma conversion, overexpression of the hepatocyte growth factor (HGF) receptor Met, but failed to confer invasiveness in vivo and in vitro, or to produce alterations in cell proliferation and differentiation." (PMID 9010033, 1997).
alopecia (3 papers, 2016 to 2025). Hair loss usually from the scalp. "The purpose of the present study is to investigate the therapeutic role of HGF in hair loss treatment." (PMID 27833804, 2016). "Similarly, a large-scale study involving over 1000 alopecia patients demonstrated significant hair growth with adipose-derived stem cell-conditioned medium (ADSC-CM) injections containing VEGF, HGF, bFGF, KGF, and PDGF, administered monthly for 6–8 sessions with no significant adverse effects." (PMID 40141845, 2025).
Anxiety (3 papers, 2011 to 2025). Intense feelings of nervousness, tension, or panic often arise in response to interpersonal stresses. "Because the amygdala has an important role in fear and anxiety, the HGF signaling pathway in the amygdala may be important for emotion." (PMID 21858037, 2011). "HGF infusion into the cerebral lateral ventricles influences anxiety in rats." (PMID 21858037, 2011).
bone metastasis (3 papers, 2018 to 2023). Transfer of a neoplasm from its primary site to bones. "Expression of HGF and matriptase was increased in bone metastasis compared with the control, while that of HAI-2 was decreased." (PMID 29890660, 2018). "However, as observed in the results of many clinical trials, the c-Met/HGF signaling is not simple, and the regulation and function of c-Met/HGF in the progression of bone metastasis necessitate extensive further investigation." (PMID 30658428, 2019).
brain cancer (3 papers, 2020 to 2023). A primary or metastatic malignant neoplasm affecting the brain. "HGF is a multifunctional growth factor that stimulates the proliferation, morphogenesis, and survival of cancer cells, including cancers of the brain." (PMID 32607415, 2020).
bronchopulmonary dysplasia (3 papers, 2013 to 2024). Bronchopulmonary dysplasia is a chronic respiratory disease that results from complications related to lung injury during the treatment of infant acute respiratory distress syndrome in low-birth-weight premature infants or from abnormal lung development in older infants. "Infants with bronchopulmonary dysplasia who have reduced HGF levels typically have worse outcomes." (PMID 23459311, 2013).
cholestasis (3 papers, 2011 to 2024). Impairment of the bile flow caused by obstruction within the liver, or outside the liver in the bile duct system. "Then, the levels of TGF-β, HGF, collagen-I and -IV mRNA, in addition to miR-29a and miR-29b were determined after HGF and TGF-β stimulation of HSC or after experimental fibrosis induced by bile-duct obstruction in rats." (PMID 21931759, 2011).
cholesteatoma (3 papers, 2018 to 2021). A pathologic process characterized by the proliferation of keratinizing squamous epithelium resulting in the accumulation of keratin and cells in the middle ear and/or mastoid. "The expression of the growth factors KGF, EGF, EREG, IGF-2 and HGF was significantly higher in fibroblasts, particularly when derived from cholesteatoma." (PMID 33627146, 2021). "This enhanced expression in vitro fits to the higher expression of KGF, IL-1α and HGF detected in vivo in cholesteatoma tissue when compared to auditory canal skin." (PMID 33627146, 2021). "Beyond this growth factors crucial for epidermal growth and wound healing, e.g. EGF, KGF, Epiregulin, bFGF, TGF-β1 and HGF, were upregulated as well in cholesteatoma tissue." (PMID 33627146, 2021). "These ME-CSCs were able to differentiate into keratinocyte-like cells after exposure to growth factors like hepatocyte growth factor and keratinocyte growth factor present in cholesteatoma tissue." (PMID 31947538, 2020). "When comparing the cells derived from cholesteatoma tissue with the cells from auditory canal skin, we could observe a significant upregulation of the two growth factors KGF and IGF-2 and a similar trend for IL-1α and HGF." (PMID 33627146, 2021).
chronic GVHD (3 papers, 2006 to 2020). "HGF gene transfection significantly inhibited proteinuria and histopathological changes associated with chronic GVHD." (PMID 16859527, 2006). "HGF transfection significantly inhibited proteinuria and histopathological changes of the kidneys, liver and salivary glands caused by chronic GVHD." (PMID 16859527, 2006). "The number of host B cells decreased by 35% in HGF gene transfected chronic GVHD mice compared to untreated chronic GVHD mice." (PMID 16859527, 2006). "In the present study, we evaluated the therapeutic and preventive effects of HGF treatment using the parent-into-F1 chronic GVHD mouse model." (PMID 16859527, 2006). "In the present study, we demonstrated that HGF inhibited the increased Th2-mediated immune response in chronic GVHD mice." (PMID 16859527, 2006). "The present study demonstrates that repeated HGF gene transfection into BDF1 mice prevents the development of chronic GVHD induced by the injection of DBA/2 spleen cells." (PMID 16859527, 2006). "Considering these results, HGF seems to not only inhibit end-organ damage through its anti-apoptotic and regenerative actions but also directly control autoimmunity in chronic GVHD mice." (PMID 16859527, 2006). "HGF treatment also inhibited mononuclear cell infiltration into the liver and salivary glands of chronic GVHD mice." (PMID 16859527, 2006). "Lastly, HGF transfection inhibited IL-4 mRNA expression in the kidneys, liver, and spleen of chronic GVHD mice." (PMID 16859527, 2006). "We determined the therapeutic effect of hepatocyte growth factor (HGF) gene transfection on lupus using this chronic GVHD model." (PMID 16859527, 2006). "Repeated transfection of the human HGF gene into skeletal muscle of chronic GVHD mice achieved a plasma HGF level (human and mouse HGF) between 1.07 and 1.35 ng/ml during the 12 week period after GVHD induction." (PMID 16859527, 2006). "Chronic GVHD mice were injected in the gluteal muscle with either HVJ liposomes containing 8 μg of the human HGF expression vector (HGF-HVJ liposomes) or mock vector (untreated control)." (PMID 16859527, 2006). "The precise mechanisms by which HGF inhibits Th2-mediated responses in chronic GVHD mice remain unclear." (PMID 16859527, 2006). "However, HGF treatment inhibited IL-4 mRNA expression in chronic GVHD target organs, splenic B cell expansion, and autoantibody production in chronic GVHD mice." (PMID 16859527, 2006). "Therefore, we examined the effect of HGF on host B cell MHC class II expression in our chronic GVHD mouse model." (PMID 16859527, 2006). "Indeed, we observed decreased MHC class II expression on host B cells from HGF-treated chronic GVHD mice." (PMID 16859527, 2006). "Thus, our results indicated that HGF may inhibit the ability of donor DBA/2 T cells to induce MHC class II expression by host BDF1 B cells in chronic GVHD mice." (PMID 16859527, 2006). "Therefore, we investigated whether HGF gene transfection induced donor anti-host CTLs in our chronic GVHD mouse model." (PMID 16859527, 2006). "As donor DBA/2 CD4+ T cells differentiate into Th2 cells in response to host BDF1 antigen presenting cells in chronic GVHD mice, we performed a DBA/2 anti-BDF1 MLR and examined the effect of HGF on the generation of Th1 and Th2." (PMID 16859527, 2006). "While untreated chronic GVHD mice expressed high levels of MHC class II antigens on host B cells, host B cells from HGF-treated chronic GVHD mice showed reduced expression." (PMID 16859527, 2006). "We examined the effect of HGF gene transfection on IL-4 and IFN-γ mRNA expression levels in target chronic GVHD organs in the mouse." (PMID 16859527, 2006). "HGF gene transfection significantly inhibited the expression of IL-4 mRNA in these organs, while IFN-γ mRNA expression levels were not significantly altered between HGF-treated and untreated chronic GVHD mice." (PMID 16859527, 2006).
chronic GVHD (continued). "HGF gene transfection also inhibited an increase in splenic B cell numbers, MHC class II expression by host B cells, and serum IgG and anti-DNA antibody concentrations in chronic GVHD mice." (PMID 16859527, 2006). "We investigated whether HGF gene transfection could prevent murine lupus in a model of chronic GVHD using non-irradiated parent spleen cells injected into F1 recipient mice." (PMID 16859527, 2006). "It is possible that HGF may decrease the expression of MHC class II antigens on host B cells, which would suppress donor CD4+ T cell activation, and so reduce the Th2 response in chronic GVHD mice." (PMID 16859527, 2006).
chronic heart failure (3 papers, 2011 to 2025). "We hypothesized that in a rat model of MI-induced chronic heart failure, this therapy could be further improved by overexpression of the antiapoptotic, antifibrotic, and proangiogenic hepatocyte growth factor (HGF) in the myoblast sheets." (PMID 21541335, 2011). "Thus both HGF and myoblast sheet therapy harbor proangiogenic potential in the ischemic myocardium and could provide a synergistic therapeutic effect even in the difficult-to-treat setting of chronic heart failure." (PMID 21541335, 2011).
chronic hepatitis (3 papers, 2010 to 2023). An active inflammatory process affecting the liver for more than six months. "When compared to chronic hepatitis as the control group, HGF levels are considerably higher in the HCC group." (PMID 37509493, 2023).
co-infection (3 papers, 2017 to 2020). "One of the mechanisms for other viral co-infection to trigger KSHV reactivation is the secretion of inflammatory cytokines, such as oncostatin M (OSM), hepatocyte growth factor (HGF), interferon-γ (IFN-γ), and Toll-like receptors 7 and 8 (TLR7/8) triggered by co-infected viruses." (PMID 28473805, 2017).
cognitive decline (3 papers, 2018 to 2025). "Higher level of baseline CSF HGF was associated with faster cognitive decline." (PMID 34615471, 2021). "Follow-up longitudinal studies can help address this limitation as well as elucidate the prognostic utility of serum HGF in predicting the course of CeVD and cognitive decline." (PMID 29410622, 2018). "High concentrations of HGF in CSF may be related to faster cognitive decline." (PMID 34615471, 2021). "Higher concentration of CSF HGF was related to higher levels of CSF markers of AD pathology and faster cognitive decline in non-demented participants." (PMID 34615471, 2021). "High concentrations of HGF in CSF may be related to AD pathology and faster cognitive decline in non-demented participants." (PMID 34615471, 2021).
demyelination (3 papers, 2013 to 2024). "The analysis of chemotactic factors in cuprizone induced demyelination revealed an increased expression of CCL-2, CXCL-10, and HGF in the corpus callosum suggesting a potential source of the CNS to attract MSC into the lesion." (PMID 23922802, 2013). "Taken together, our results indicate that the expressions of c-Met and KAI-1 possibly reflect the degree of inflammation and that the expression level of HGF regulates the balance between the HGF/c-Met pathway and the HGF/KAI-1 pathway during both EAE- and CPZ-induced demyelination." (PMID 39457044, 2024).